CRP (C-reactive protein)
Diseases named in the same sentence as CRP in open-access papers (continued):
Sharing a sentence is not in itself a finding about the gene and the disease.
appendicitis (continued). "However, it is still unknown whether PSP is superior to other established blood tests (e.g. WBC or CRP) in predicting appendicitis in patients presenting with abdominal pain and a clinical suspicion of appendicitis at the emergency room." (PMID 23098130, 2012). "Traditional diagnostic approaches include clinical scoring systems such as the Pediatric Appendicitis Score (PAS), laboratory markers such as WBC count and CRP, and imaging modalities such as ultrasound and CT." (PMID 41517643, 2026). "Patients with appendicitis were significantly older (p = 0.0012), exhibiting elevated white blood cells(WBC) count, neutrophils, and C-reactive protein (CRP) levels, and lower lymphocytes (all p < 0.001)." (PMID 41632773, 2026). "Our study demonstrates CRP, and to a lesser extent NLR, as effective and affordable biomarkers in predicting acute appendicitis in paediatric patients, and by extension preventing the need for unnecessary appendicectomy." (PMID 41523465, 2025). "In children with pathohistologically confirmed acute appendicitis, the median salivary CRP level was 35.7 mg/L (IQR 15.9–114.3), significantly higher than in the control group, where the median CRP was 1.1 mg/L (IQR 0.2–2.7) (p < 0.001)." (PMID 40871545, 2025). "Interestingly, salivary CRP has also been investigated and shows good correlation with serum levels, suggesting saliva might provide a less invasive alternative for monitoring systemic inflammation in appendicitis." (PMID 41153524, 2025). "Still, it was lower than the AUCs for C-reactive protein (CRP) and Appendicitis Inflammatory Response (AIR) score." (PMID 40208339, 2025). "Patients with complicated appendicitis had significantly higher mean WCC (15.2 vs 11.9 ×109/L; p < 0.001), CRP (115.8 vs 57.3 mg/L; p < 0.001), and age (41.7 vs 32.6 years; p = 0.001)." (PMID 41250717, 2025). "C-reactive protein (CRP), routinely measured from blood samples, is one of the most important pro-inflammatory biomarkers in acute appendicitis." (PMID 40871545, 2025). "The study included 191 children randomized into two groups: one evaluated using the standard protocol [pediatric appendicitis score (PAS), C-reactive protein (CRP) and ultrasound] and the other with the addition of urinary 5-HIAA measurement." (PMID 40547910, 2025). "Blood results often show elevated CRP, elevated WBC counts, and the presence of polymorphonuclear leukocytes in acute appendicitis presentation." (PMID 40642732, 2025). "Absolute neutrophil count (ANC), absolute platelet count (APC), absolute monocyte count (AMC), CRP, NLR, PLR, NMR, NPR were higher in the appendicitis group, whereas absolute lymphocyte count (ALC) and MLR were lower in the appendicitis group." (PMID 40317523, 2025). "The aim of this study is to assess the utility of C-reactive protein (CRP) and neutrophil-lymphocyte ratio compared to standard biochemical markers in predicting acute appendicitis and preventing unnecessary appendicectomy." (PMID 41523465, 2025). "In contrast to this patient, a systematic review found that elderly patients with complicated appendicitis often presented with higher WBC, CRP, and total bilirubin and lower lymphocyte levels." (PMID 41357729, 2025). "Several studies demonstrate that elevated serum bilirubin correlates with gangrenous or perforated appendicitis, with a specificity higher than that of white blood cell count (WBC) and CRP." (PMID 41230472, 2025). "Most inflammatory markers, including WBC, neutrophil count (NEU), CRP, NLR, PLR, and SII, were significantly elevated in the appendicitis group compared to controls (p < 0.001 for all)." (PMID 40804906, 2025). "Appendicitis was more frequently observed in patients presenting with RLQ pain (p = 0.018) and in those with elevated CRP levels (CRP > 20 mg/L) (p = 0.012)." (PMID 40999376, 2025).
appendicitis (continued). "CRP level at admission and three hours post, as well as initial Modified Alvarado score (MAS), were identified, and their utility in predicting acute appendicitis on histopathology explored." (PMID 41523465, 2025). "Generally, patients with appendicitis on histopathology demonstrated higher WCC and neutrophil counts, CRP and NLR value, whereas patients with normal appendiceal tissue or E. vermicularis demonstrated a higher eosinophil and lymphocyte count, and NER value." (PMID 41523465, 2025). "In terms of thresholds at which feature values increase the probability of appendicitis, we see a lot of similarity to AIR score cutoffs—around 10 mg/L for CRP, 10 × 109/L for WBC count, and 80% for neutrophils percentage." (PMID 38834671, 2024). "When reviewing patients' biochemical findings in those where a histological diagnosis of appendicitis was made, eight (100%) patients were noted to have a rise in white cell count (WCC), neutrophils, and C-reactive protein (CRP)." (PMID 39640104, 2024). "The investigation also sheds light on the relationship between CRP and LOS in various scenarios, offering a fresh perspective on the role of CRP in pediatric appendicitis." (PMID 39726534, 2024). "Patients with perforated appendicitis were younger, had a longer onset time, and exhibited elevated inflammatory markers, including WBC, CRP, and NLR, compared to the suppurative and gangrenous groups (all p < 0.05)." (PMID 39735250, 2024). "The findings of our study indicate a significant positive correlation between CRP and LOS in patients with appendicitis." (PMID 39726534, 2024). "Study data showed that 100% of patients who had a positive diagnosis of appendicitis were noted to have a rise in WCC, neutrophils, and CRP." (PMID 39640104, 2024). "The current study reinforces the benefits of using CRP and MAS in combination when predicting acute appendicitis." (PMID 39677268, 2024). "C-reactive protein (CRP) and blood leukocyte count were significantly higher in children with complex compared to simple appendicitis." (PMID 38239362, 2023). "The unfavourable development of appendicitis may result in the development of a generalised inflammatory reaction (including, among others, increased production of pro-inflammatory cytokines and acute phase proteins, i.e., CRP, PCT, and NGAL) leading to bacterial sepsis." (PMID 37509519, 2023). "Elevated CRP and WBC levels indicate advanced appendicitis in children, with optimal cutoff values of 14,000/mm3 and 3.9 mg/dL, respectively." (PMID 36900066, 2023). "The intraluminal air, transverse diameter of the appendix, ascites, CRP, WBC, ESR, and body temperature were selected as important features for predicting complicated appendicitis." (PMID 36900066, 2023). "This study aimed to evaluate and compare the diagnostic accuracy of circulating fibrocyte percentage (CFP), white blood cell count, C-reactive protein, and neutrophil-lymphocyte ratio (NLR) in diagnosing uncomplicated and complicated appendicitis." (PMID 37093074, 2023). "Complicated appendicitis was found in old patients with high neutrophil and lymphocyte, neutrophil to lymphocyte ratio (NLR), CRP, diameter, and position of the appendix (from abdominal ultrasound)." (PMID 37090195, 2023). "In other inflammatory conditions such as acute pancreatitis, appendicitis, and cholangitis, PCT was more useful in severity stratification than CRP." (PMID 37109763, 2023). "We can conclude that the sensitivity of CRP is higher than WBC, which makes it a better test for screening and ruling in appendicitis." (PMID 37873039, 2023). "The main objective of this study is to decipher the incline of CRP, TLC and neutrophils in acute appendicitis and their ability to predict complications and perforation in the pediatric age group." (PMID 35495380, 2022).
appendicitis (continued). "In order to determine cut-off points with their sensitivity and specificity, we made two ROC curves using as an independent variable, the diagnosis of appendicitis peritonitis and as dependent variables, NLR, PLR, CRP, fibrinogen, and ESR." (PMID 36676645, 2022). "Most patients with complicated appendicitis had elevated inflammatory markers including WBC (median, 17.1 ± 5.7 cells/L) and CRP (median, 13.8 ± 9.0 mg/dL)." (PMID 35463908, 2022). "The best performing single blood tests for ruling-out paediatric appendicitis are WCC or ANC; with accuracy improved combining WCC and CRP." (PMID 36328382, 2022). "The aim of this study was to determine the benefits of using three inflammatory markers, white blood count (WBC), neutrophils percent (NE%), and C-reactive protein (CRP), in ruling out appendicitis in pediatric patients." (PMID 36514558, 2022). "In this study, the status of the inflammatory process in acute appendicitis was examined with the dynamic thiol-disulfide balance and other laboratory tests (WBC, CRP, MPV, total bilirubin) at the time of admission to the hospital and before discharge." (PMID 36225527, 2022). "A combination of CRP and WCC (11 studies, 2497 patients, 1008 appendicitis) demonstrated a sensitivity range of 0.34–0.80 and specificity range of 0.50–0.95." (PMID 36328382, 2022). "Although an increase in WCC has no significant predictive value in distinguishing between uncomplicated and complicated appendicitis, WSES advises absolute neutrophil count and CRP to predict severity of inflammation." (PMID 36185898, 2022). "PCT is less accurate than CRP and WBC in the diagnosis of acute appendicitis, but more accurate in the diagnosis of CA." (PMID 35431963, 2022). "The main objective of this study is to decipher the ability of CRP, TLC and neutrophils in acute appendicitis to predict complications and perforation in pediatric age group." (PMID 35495380, 2022). "Patients with complicated appendicitis had significantly higher WCC, neutrophil, and CRP levels than those with uncomplicated appendicitis (14.15 vs. 12.88, p = 0.016; 11.63 vs. 10.19, p = 0.007; and (89.28 vs. 40.65, p = 0.0001, respectively).." (PMID 36237793, 2022). "A study conducted on pediatric population concluded a higher odd of perforated appendicitis with raised TLC, neutrophils combined with CRP levels." (PMID 35495380, 2022). "This study confirms that increased bilirubin levels can indicate complicated appendicitis with better accuracy and sensitivity than WCC and CRP (73.9 vs. 62% vs. 68%, and 73.3 vs. 68.2% vs. 61.1%, respectively)." (PMID 36237793, 2022). "The ROC analysis revealed that in predicting complicated appendicitis, the AUC values of leukocyte, DNI%, and CRP were 0.607, 0.671, and 0.709, respectively." (PMID 33936912, 2021). "In case 2, we anticipated the development of appendicitis because of the slightly elevated WBC and CRP levels, and therefore administered antibiotics." (PMID 34807319, 2021). "Our study confirmed that the new developed models employing three grades of FS, in combination with biomarkers of CRP or NLR and CT features of appendicolith or ascites, were powerful to identify complicated acute appendicitis." (PMID 34645500, 2021). "By exploration of different cut-off values for WBCs and CRP, a maximal NPV of 88% can be reached for ruling out appendicitis." (PMID 33851877, 2021). "In the ROC analysis for the prediction of acute appendicitis, the area under the curve (AUC) values of leucocyte, DNI%, and CRP were 0.780, 0.741, and 0.611, respectively." (PMID 33936912, 2021). "Diagnosis of acute appendicitis in children mainly depends on PAS, complete blood count and determination of serum level of C- reactive protein." (PMID 33898036, 2021). "Multivariable logistic regression analysis of CRP, PAS and urinary 5-HIAA were performed to assess the independent variables for the prediction of acute appendicitis." (PMID 33898036, 2021).
appendicitis (continued). "Another score is the adult appendicitis score (AAS), which uses clinical data, white cell count, and CRP level." (PMID 33520210, 2021). "CT: computerised tomography; USS: ultrasound scan; AA: acute appendicitis; WCC: White cell count; CRP: c-reactive protein." (PMID 33927917, 2021). "There are no specific laboratory parameters specific to the diagnosis of acute appendicitis, but WBC and CRP are widely used for this purpose." (PMID 34646676, 2021). "In the analysis of the total cohort matched for age and gender, CRP, WBC and percentage of neutrophils were significantly higher in complicated appendicitis and in gangrenous appendicitis (p < 0.001)." (PMID 33060696, 2020). "Five independent predictors of acute appendicitis included vomiting, right lower quadrant (RLQ) pain, stool occult blood (OB), white blood cell (WBC) count, and C-reactive protein (CRP)." (PMID 33050667, 2020). "For now, the diagnosis of acute appendicitis mainly depends on patient symptoms and serological results, such as white blood cell count (WBC), C-reactive protein (CRP), and neutrophil cells." (PMID 32337245, 2020). "Of interest was the finding that a total of 38.9 of patients with normal CRP and WCC had appendicitis." (PMID 32983436, 2020). "The degree of inflammation in the acute appendicitis was low with high WBC and CRP levels, and it correlated with serum FA concentration." (PMID 31547519, 2019). "While all of these values were significant in univariate regression analysis of perforated appendicitis group, only WBC, CRP, and FA levels were significant in multiple linear regression analysis." (PMID 31547519, 2019). "In pediatric abdominal pains, low serum FA levels, and high CRP and WBC levels, physical examination, and radiological imaging increase the accuracy rate in the diagnosis of acute appendicitis." (PMID 31547519, 2019). "We calculated the sensitivity, specificity, positive and negative predictive values, the likelihood ratios in the diagnosis of appendicitis for white blood cell (WBC), neutrophil count, c-reactive protein (CRP), MPV, and PDW values were calculated." (PMID 31183274, 2019). "Positive CRP levels (>0.6 mg/dl), USG diagnosing appendicitis, total WBC counts (>10,000), differential neutrophil counts (N>75%), an Alvarado score (> 4) between the groups were statically significant (p>0.05)." (PMID 29552432, 2018). "In patients with acute appendicitis mean WBC and CRP measurements were significantly higher than in the patients with normal appendix (both p < 0.01)." (PMID 29793425, 2018). "In comparison between acute simple and complicated appendicitis, only DNI and CRP were significantly different between the groups." (PMID 28747992, 2017). "Two scores, with the purpose of ruling out appendicitis, were created, with integration of US with PAS and/or CRP." (PMID 28044133, 2016). "The Appendicitis Inflammatory Response (AIR) score has been proposed in 2008 by Andersson and is based on eight variables, including C-reactive protein (CRP)." (PMID 27437029, 2016). "Combined use of cut-off values of WBC (≥13100/μL) and CRP (≥1.17 mg/L) yields a higher sensitivity and NPV for the diagnosis of complicated appendicitis." (PMID 27274988, 2016). "Complicated appendicitis can be predicted by RPS count, diameter of the appendix, appendicolithiasis, and CRP level." (PMID 25587352, 2014). "Univariate analysis revealed that patients with complicated appendicitis were more likely to have higher RPS count (P < 0.001), higher CRP level (P < 0.001), greater appendix diameter (P < 0.001), and appendicolitiasis (P = 0.002)." (PMID 25587352, 2014). "In the older patient group, patients with complicated appendicitis were more likely to have higher RPS count (P < 0.001), higher CRP level (P < 0.001), greater appendix diameter (P = 0.002), appendicolitiasis (P = 0.04), and advanced age (P = 0.01)." (PMID 25587352, 2014).
appendicitis (continued). "Recently, one systematic review and meta-analysis reported imperfect accuracy of procalcitonin, C-reactive protein (CRP) and white blood cell count (WBC) in uncomplicated or complicated appendicitis." (PMID 25587352, 2014). "CRP, leukocyte count, and MPV level were significantly higher in the acute appendicitis group (P < 0.001)." (PMID 24693387, 2013). "Comparison of the demographic features and leukocyte count, CRP, and MPV levels of the subjects in the acute appendicitis and the control groups." (PMID 24693387, 2013). "However, it is not known whether PSP is superior to other established blood tests (e.g. White Blood Count, Neutrophils or C - reactive protein) in predicting appendicitis in patients presenting with abdominal pain and a clinical suspicion of appendicitis at the emergency room." (PMID 23098130, 2012). "The aim of this study was to analyze the role of C-reactive protein (CRP) values, in accuracy of diagnosis of acute appendicitis in comparison with WBC, NP, the surgeon's clinical diagnosis, and the histopathologic findings." (PMID 22866907, 2012). "A study was conducted on 110 patients who were operated for acute appendicitis to determine the role and predictive value of the total leucocyte count (TLC), C-reactive protein (CRP) and percentage of neutrophil count in the diagnosis of acute appendicitis." (PMID 19568576, 2009). "The variability in timing may confound biomarker performance, especially because CRP, which is highly time dependent, is a significant component of CLR, which was found to be the best predictor of complicated appendicitis." (PMID 41517643, 2026). "Dharma first performs robust imputation of features frequently missing in resource-constrained settings—such as C-reactive protein (CRP), appendiceal diameter, free fluid, and urinary ketones—using the Dharma Imputer, a model pre-trained on the appendicitis cohort." (PMID 41564021, 2026). "Further research might explore the combined use of CRP, MPV, and NLR to develop a comprehensive biomarker profile for appendicitis diagnosis and severity assessment." (PMID 39764342, 2025). "These larger differences—in both directions (positive and negative)—were primarily observed at higher serum CRP levels and predominantly among children with acute appendicitis." (PMID 40871545, 2025). "CRP concentrations were significantly higher among the patients with complicated appendicitis compared to the patients with no or uncomplicated appendicitis (p < 0.001)." (PMID 40208339, 2025). "During the acute inflammatory phase of appendicitis, the positive acute-phase protein CRP increases, while the negative acute-phase protein albumin decreases." (PMID 41141923, 2025). "In contrast, we observed higher CRP (C-reactive protein) levels in the Campylobacter group compared to cases with simple appendicitis, but not compared to those with complicated appendicitis." (PMID 40901534, 2025). "Specifically, both WBC count and CRP within the normal range have a high negative predictive value for acute appendicitis." (PMID 40400853, 2025). "These scales include only variables related to immune cells or inflammatory-related markers such as C-reactive protein; however, other important biochemical parameters involved in the appendicitis pathophysiology have not been considered." (PMID 40806903, 2025). "Although IL-6 is considered an inflammatory marker in appendicitis, it does not appear to provide a significant diagnostic advantage over traditional markers like WBC and CRP." (PMID 41153524, 2025). "CRP is superior to NLR, neutrophil and lymphocyte count in predicting acute appendicitis." (PMID 41523465, 2025). "On the other hand, most patients with acute appendicitis have a WBC count >10,000 cells/mm3, and a significantly increased WBC count >17,000 cells/mm3, in addition to elevated CRP, may indicate complicated appendicitis." (PMID 40400853, 2025).